CD4 (CD4 molecule)
Diseases named in the same sentence as CD4 in open-access papers (continued):
Sharing a sentence is not in itself a finding about the gene and the disease.
eosinophilic disorders (1 paper, 2024). "Notable among genes that shared expression patterns among eosinophilic disorders compared to controls was the upregulation of MTRNR2L1 in four level one cell types (B, CD4+ T, CD8+ T, and DC) and upregulation of several cell cycle associated genes in CD4+ T cells." (PMID 39192974, 2024).
eosinophilic enteritis (1 paper, 2020). "Five cats had gastrointestinal histology performed: 3 CD4+ T‐cell cats were diagnosed with intestinal lymphoma, 1 heterogeneous case had lymphoplasmacytic and eosinophilic enteritis, and 1 CD8+ T‐cell case had lymphocytic gastritis with associated helicobacter organisms." (PMID 31693230, 2020).
Epstein-Barr virus infection (1 paper, 2013). An infection that is caused by Epstein-Barr virus. "Our case has suffered from stage IV ALCL with an extremely low baseline CD4 count (26/μL) not Epstein-Barr virus infection, but has survived more 5 years without remission by chemotherapy and ART." (PMID 24010049, 2013).
erythema multiforme major (1 paper, 2024). A severe, sometimes life-threatening, form of erythema multiforme. "In conclusion, PD-L1 expression in keratinocyte and infiltration of CD4 + lymphocyte can predict a severe type of erythema multiforme major induced by Pem." (PMID 38962048, 2024).
esophageal motility disorders (1 paper, 2025). "Interestingly, studies investigating IELs in patients with esophageal motility disorders have reported a reverse CD4:CD8 ratio, with a predominance of CD4+ T cells." (PMID 41458336, 2025).
Esophageal stricture (1 paper, 2019). A pathological narrowing of the esophagus that is caused by the development of a ring of scar tissue that constricts the esophageal lumen. "To our knowledge, we report the first pediatric case of esophageal stricture secondary to CMV infection related to IRIS; moreover, CD4% during the IRIS event was >25, corroborating the view that CD4% is not a reliable marker for disease progression and severity in infants." (PMID 31355171, 2019).
esophageal ulceration (1 paper, 2026). "Idiopathic esophageal ulceration (IEU) is a diagnosis of exclusion associated with profound immunosuppression, typically with CD4 counts <50 cells/mm3." (PMID 41755919, 2026).
Fabry disease (1 paper, 2019). Fabry disease (FD) is a progressive, inherited, multisystemic lysosomal storage disease characterized by specific neurological, cutaneous, renal, cardiovascular, cochleo-vestibular and cerebrovascular manifestations. "Here, we studied the percentage of total iNKT cells and their CD4/CD8 phenotype in the blood of Gaucher, NPC, and MPS-VI disease patients compared with control individuals and our own published data on Fabry disease patients." (PMID 31214199, 2019).
Facial palsy (1 paper, 2010). Facial nerve palsy is a dysfunction of cranial nerve VII (the facial nerve) that results in inability to control facial muscles on the affected side with weakness of the muscles of facial expression and eye closure. "HIV serology was found positive during workup for the cause of his bilateral facial palsy, CD4+ count was decreased at that time." (PMID 21118561, 2010). "Case 4 had a moderately low CD4+ count and had a classical course of EM, followed by malaise and a facial palsy with signs of early LNB in serology of CSF and serum." (PMID 21118561, 2010).
facial paralysis (1 paper, 2012). Severe or complete loss of facial muscle motor function. "One Mexican study of 92 patients with IFP found a significant decrease in the HLA class 2 DR antigen and acutely decreased levels of CD3/CD4 T cells at the onset of facial paralysis, suggesting the possibility that an HLA-DR linked “resistance gene” may exist." (PMID 22934210, 2012).
Felty syndrome (1 paper, 2025). Felty syndrome (FS), also known as ''super rheumatoid'' disease, is a severe form of rheumatoid arthritis (RA), characterized by a triad of RA, splenomegaly and neutropenia, resulting in susceptibility to bacterial infections. "Although the patient had normal CD4+ and CD8+ levels after diagnosis with Felty’s syndrome." (PMID 40255577, 2025).
floor of mouth tumors (1 paper, 2022). "CD4- expression were associated with floor of mouth tumors (p=0.004)." (PMID 35957892, 2022).
focal epilepsy (1 paper, 2025). A seizure caused by a localized disorder. "The mechanisms, such as localized neuroinflammation, CD4+ T cell exhaustion, hippocampal sclerosis, or region-specific immune dysregulation, may explain the role of the immune system in focal epilepsy." (PMID 40868440, 2025).
focal seizure (1 paper, 2025). "When the focal and generalized seizure subgroups were compared, the same results were found except for the CD4/CD8 ratio, which was significantly lower in the focal seizure group (p = 0.006)." (PMID 40868440, 2025).
gallbladder NET (1 paper, 2021). "The immunosuppressive TME in epithelial GC consist of infiltrating CD4+ T‐reg, CXCL13+ Th cells, CCL20lo/CD163hi, and APOE+ macrophages; however, it is the immune‐desert phenotype for gallbladder NET." (PMID 34185421, 2021).
gastric neuroendocrine tumors (1 paper, 2021). "The purpose of this study was to characterize the densities of CD3+, CD8+, CD4+ and FOXP3+ T cells in small bowel neuroendocrine tumors (SB-NETs), SB-NET lymph node metastases and gastric neuroendocrine tumors (G-NETs) to assess the prognostic role of immune cell infiltrates in SB-NETs." (PMID 34208144, 2021).
gastroschisis (1 paper, 2019). Gastroschisis is marked by viscera protruding, without a covering sac, from the fetal abdomen on the right lateral base of the umbilicus. "In this context, patients with gastroschisis have shown significant high systemic levels of inflammatory cytokines and chemokines, including an earlier activation of CD4+ and CD8+ effector and memory T cells." (PMID 31075877, 2019).
generalized seizure (1 paper, 2025). "Despite the small number of patients, we found that the CD4/CD8 ratio of the patients who had focal seizures was significantly lower than that of the generalized seizure group in our study." (PMID 40868440, 2025).
Gliosis (1 paper, 2008). Gliosis is the focal proliferation of glial cells in the central nervous system. "Lymphocytic infiltration and gliosis are common pathological findings in viral panencephalitis, with CD4+ T lymphocytes being observed in perivascular areas and CD8+ lymphocytes in the parenchyma." (PMID 18320052, 2008).
glossitis (1 paper, 2022). Inflammation of the tongue. "The second most common clinical sign was the median rhomboid glossitis (MRG), out of which the majority appeared in the HAART− group with a prevalence of 26.6% and a mean CD4+ T-cell count of <150 cells/μl." (PMID 35250957, 2022).
glucose metabolism disorders (1 paper, 2015). "Glucose metabolism disorders were significantly associated with higher CD4+ T-cell counts." (PMID 26287742, 2015).
glycosylation disorders (1 paper, 2025). "Lastly, CD4 is connected to glycosylation disorders, reproductive processes, and FGFR4 signaling." (PMID 40787634, 2025).
gram-negative bacterial infections (1 paper, 2018). Infections caused by bacteria that show up as pink (negative) when treated by the gram-staining method. "For other chronic Gram-negative bacterial infections, depletion of both CD4+ and CD8+ T cells resulted in significantly worse infection phenotypes than single depletions did." (PMID 30543708, 2018).
grand mal epilepsy (1 paper, 2023). "Her condition deteriorated rapidly with grand mal epilepsy and acute gastrointestinal bleeding with a grossly depressed CD4 T-cell count, which was indicative of her profoundly immunosuppressed state." (PMID 37781385, 2023).
hand, foot and mouth disease (1 paper, 2012). A clinical syndrome that is usually caused by enterovirus infection, and that is characterized by fever, anorexia, and painful sores in the mouth, distal extremities, and/or other sites, including the buttocks. "However, the role of CD4+ T cells in EV71 infection, which causes hand, foot and mouth disease (HFMD), has yet to be elucidated." (PMID 23251663, 2012).
HELLP syndrome (1 paper, 2020). A life-threatening condition that can potentially complicate pregnancy. "There was a significant number of CD3+CD4+ T cells in response to HELLP syndrome and in HELLP+AKI rats." (PMID 32972452, 2020).
hemarthrosis (1 paper, 2024). Bleeding into the joints. "Taken together, our study revealed a pathological joint–liver axis mediated by matrikine-activated CD4+ T cells, which refreshes the organ-crosstalk axis and provides a new treatment target for hemarthrosis-related disease." (PMID 38714712, 2024). "Flow cytometric measurement of CD4+ T cells in mouse peripheral blood, mouse spleen and human peripheral blood also showed the significant increase after hemarthrosis." (PMID 38714712, 2024). "Taken together, we revealed that CD4+ T cells are activated during hemarthrosis, while systemic deletion of CD4+ T cells blocks hemarthrosis-induced liver abnormality." (PMID 38714712, 2024). "Next, we found that hemarthrosis induces the upregulation in ratio and differentiation towards Th17 cells of CD4+ T cells in peripheral blood and spleen." (PMID 38714712, 2024). "To determine whether sCOL II could directly activate CD4+ T cells, we extracted mixed splenocytes or only CD4+ T cells sorted from splenocytes from the hemarthrosis model." (PMID 38714712, 2024). "Degeneration of cartilage matrix induced by hemarthrosis upregulates serological type II collagen (COL II), which activates CD4+ T cells." (PMID 38714712, 2024).
Hematuria (1 paper, 2018). The presence of blood in the urine. "The significant associations of TLC, proteinuria, leukocyturia, and hematuria with CD4 count indicate that these markers play a synergistic role in the pathophysiology of HIV infections." (PMID 29606987, 2018).
hereditary spherocytosis (1 paper, 2023). Hereditary spherocytosis is a congenital hemolytic anemia with a wide clinical spectrum (from symptom-free carriers to severe hemolysis) characterized by anemia, variable jaundice, splenomegaly and cholelithiasis. "He had historically low CD4+ counts, fully responded to IVIG, and had undiagnosed hereditary spherocytosis." (PMID 37243210, 2023).
hiatal hernia (1 paper, 2026). "The negative correlation between distal esophageal dilation and BAL CD4+ counts, plus the link between hiatal hernia and neutrophilic inflammation, suggests an interplay between esophageal dysfunction and the pulmonary immune microenvironment." (PMID 41827177, 2026).
HTLV-2 infection (1 paper, 2022). "In addition, while HTLV-1 has tropism to CD4+ T cells, HTLV-2 is tropic to CD8+ T cells, which can explain part of the different outcomes observed in HTLV-1 and HTLV-2 infections." (PMID 35359787, 2022).
Hypercalciuria (1 paper, 2012). "Normal serum ACE levels, absence of hypercalciuria, normal pulmonary function tests, slit-lamp eye examination, CD4 to CD8 ratio in bronchoalveolar lavage, and no detection of sarcoid granulomata in gastrocnemius muscle biopsy, made this diagnosis unlikely." (PMID 23078628, 2012).
Hypernatremia (1 paper, 2019). An abnormally increased sodium concentration in the blood. "Hypertonicity-activated NFAT5 also enhances the expression of the Th17 master transcription regulator RORγt, to whose promoter NFAT5 is recruited in mouse CD4 T cells exposed to hypernatremia, and induces IL-23R in a RORγt-dependent manner." (PMID 30949179, 2019). "NFAT5 was also recently shown to enhance expression of IL-2 mRNA in activated primary mouse CD4 T cells exposed to hypernatremia." (PMID 30949179, 2019).
hyperplastic polyp (1 paper, 2022). A polyp found mainly in the stomach and colon. "Interestingly, all of the polyps samples that showed CD4 T cell response against PASD1 peptides were from hyperplastic polyps, a type of polyps with less association with cancer development." (PMID 37529004, 2022).
hypertrophic cardiomyopathy (1 paper, 2025). A condition in which the myocardium is hypertrophied without an obvious cause. "In addition, BPIFC was involved in the infiltration of naïve T CD4+ cells and T CD8+ cells in hypertrophic cardiomyopathy." (PMID 41153404, 2025).
hypoparathyroidism (1 paper, 2023). Hypoparathyroidism is an endocrine disorder in which the parathyroid glands in the neck do not produce enough parathyroid hormone (PTH). "Moreover, in a recent study aiming at evaluating the immune function in patients with chronic postsurgical hypoparathyroidism, immune cell profiling revealed a decline in different immune cell populations including monocytes and regulatory, naïve, and total CD4+ lymphocytes." (PMID 37180074, 2023).
hyposplenism (1 paper, 2020). "The reduction in the proportion of circulating CD4+ and CD8+ cells was shown to be more profound in the presence of splenic defects, and SCA is invariably accompanied by hyposplenism." (PMID 32411797, 2020).
idiopathic anterior uveitis (1 paper, 2023). "This is confirmed by literature data - studies of the local immune response: in the intraocular fluid of the anterior chamber in Fuchs uveitis, CD8+ T cells were higher than in idiopathic uveitis, and the number of CD4+ cells was higher in idiopathic anterior uveitis than in Fuchs uveitis." (PMID 37089809, 2023).
idiopathic intracranial hypertension (1 paper, 2025). "For peripheral blood cells, we found upregulation of ARHGAP27 (Rho GTPase-activating protein 27) in CD4+ and CD8+ lymphocytes in MS patients compared to negative controls (idiopathic intracranial hypertension patients)." (PMID 40242760, 2025).
ileocolitis (1 paper, 2022). Ileocolitis or ileal Crohn's is the most common type of Crohn's disease. "To determine the impact of the microbiome on the intestinal T cell activation associated with AGR2-dependent ileocolitis, we profiled ileal lamina propria CD4+ T cells in SPF Agr2−/− mice with ileocolitis." (PMID 36384110, 2022).
Impotence (1 paper, 2022). Inability to develop or maintain an erection of the penis. "Furthermore, CD4+TIL-Ts are required for CD8+ TIL-T activation, and their depletion may result in CD8+ TIL-T impotence." (PMID 36325319, 2022).
inflammatory demyelinating neuropathies (1 paper, 2015). "Here, rats preconditioned with forced exercise were found to exhibit a sustained protection against the development and progression of experimental autoimmune neuritis (EAN), an established CD4+ T-cell dependent rat model of human inflammatory demyelinating neuropathies." (PMID 26186926, 2015).
insulinoma (1 paper, 2023). "The memory CD4 T cells, immature B cells, and immature dendritic cells are significantly enriched in insulinoma tissue." (PMID 37772258, 2023).
interstitial cystitis (1 paper, 2015). A rare chronic debilitating urogenital disease characterized by urinary frequency, urgency, and pelvic pain. "Indeed, we have previously shown that CD4 and CD8 T cell responses occur following single immunizations with α-lactalbumin and uroplakin II for effective induction of autoimmune breast failure and interstitial cystitis, respectively." (PMID 26618181, 2015).
intervertebral disc disorders (1 paper, 2023). "Additionally, we observed that other intervertebral disc disorders significantly increase the risk of CD39+ CD4+ T cell %CD4+ T cell (OR: 1.409, 95%CI: 1.053-1.885, p=0.021)." (PMID 38268919, 2023). "For the bidirectional MR analysis between CD39+ CD4+ T cell %CD4+ T cell and other intervertebral disc disorders, both the p-values of Cochran’s Q and MR-Egger intercept were greater than 0.05, suggesting the absence of heterogeneity and pleiotropy." (PMID 38268919, 2023). "Results of sensitivity analysis between other intervertebral disc disorder and the risk of CD39+ CD4+ T cell %CD4+ T cell." (PMID 38268919, 2023).
intestinal lymphangiectasia (1 paper, 2023). Dilatation of the intestinal lymphatic system usually caused by an obstruction in the intestinal wall. "The presence of systemic disease, genital oedema, and intestinal lymphangiectasia independently predict CD4 lymphopaenia." (PMID 38022535, 2023).
Intussusception (1 paper, 2020). An abnormality of the intestine in which part of the intestine invaginates (telescopes) into another part of the intestine. "This study confirmed that before intussusception reduction, serum CD4+, CD3+, CD8+, etc. were reduced to varying degrees." (PMID 33235589, 2020).
iridocyclitis (1 paper, 2014). "Fungal chorioretinitis involved Candida and fumigatus, in patients with CD4 < 200/μL and concomitant injuries of anterior ocular segment (iridocyclitis)." (PMID 25408764, 2014).
iris tumor (1 paper, 2016). "In the second case, a 15-year-old boy with idiopathic CD4+ T-lymphocytopenia developed epithelial keratitis, an anterior chamber reaction, and iris tumor in the left eye." (PMID 27528053, 2016).
iritis (1 paper, 2007). Inflammation of the iris. "One patient, rheumatoid factor-positive and HLA-B27-positive, with iritis had no CD4+CD28null T cells either in blood or the synovial fluid." (PMID 17825098, 2007).
ischemia reperfusion injury (1 paper, 2021). Adverse functional, metabolic, or structural changes in ischemic tissues resulting from the restoration of blood flow to the tissue (reperfusion), including swelling; hemorrhage; necrosis; and damage from free radicals. "Furthermore, CD4/CD8 double-negative T cells were discovered to have a pathogenic role in early renal injury after ischemia-reperfusion injury (IRI)." (PMID 34849375, 2021).
kidney infection (1 paper, 2022). "Previous studies have showed that a low CD4/CD8 ratio in HIV-infected patients identifies greater immune defects, which might be at a higher risk of mortality, various infections, including kidney infection." (PMID 35222339, 2022).
laryngitis (1 paper, 2019). An acute or chronic, bacterial or viral inflammatory process affecting the larynx. "In HIV-infected patients with low CD4 T cell counts, T. marneffei oro-pharyngo-laryngitis may present as a part of disseminated talaromycosis." (PMID 31805893, 2019).
Left atrial enlargement (1 paper, 2024). Increase in size of the left atrium. "The most common abnormality in our study population was left atrial enlargement, which has been associated with a lower CD4+ count." (PMID 38256597, 2024).
leiomyoma (1 paper, 2019). A well-circumscribed benign smooth muscle neoplasm characterized by the presence of spindle cells with cigar-shaped nuclei, interlacing fascicles, and a whorled pattern. "Based on the fact that chronic infections are related to the etiology of leiomyoma, our results on the association between CD4/CD8 CM cells and leiomyoma seem to be biologically plausible." (PMID 31772580, 2019). "Compared with healthy controls, central memory (CM) CD4/CD8 T cells as well as Treg and Tfh cells were notably increased in leiomyoma patients; however, NK and γδ T cells were decreased in patients." (PMID 31772580, 2019).
leptomeningeal melanoma (1 paper, 2025). A melanoma that arises from leptomeningeal melanocytes. "The study of metastatic leptomeningeal melanomas has shown a highly immunosuppressive microenvironment enriched with T-cell populations, with a low percentage of CD4 and NK T-cells but a high percentage of CD8 T-cells." (PMID 41536409, 2025).
lichen planopilaris (1 paper, 2024). Lichen planopilaris (LPP) is an inflammatory condition that causes patchy hair loss, mainly on the scalp. "In contrast, the dermis of lichen planopilaris was characterized by a deficiency in CD4+T cells and a less pronounced presence of Tregs (3.51%) compared to the dermis of other LP subtypes." (PMID 39273670, 2024).
lipomatosis (1 paper, 2021). A neoplastic process characterized by diffuse overgrowth of mature adipose tissue. "A decreased number of CD3, CD4, and CD8 is present in Roch-Leri lipomatosis." (PMID 34187516, 2021).